IGF2BP2 (insulin like growth factor 2 mRNA binding protein 2)
Diseases named in the same sentence as IGF2BP2 in open-access papers (continued):
Sharing a sentence is not in itself a finding about the gene and the disease.
cancer (continued). "We believe that this is because endogenous IGF2BP2 is highly expressed in cancer cells such as the Huh7.5 cells used here and is presumably not limiting for viral replication in this system." (PMID 39565347, 2024). "Some ncRNAs can enhance RNA binding processes that promote cancer progression, while others can competitively bind to the KH domains of IGF2BP2." (PMID 39596216, 2024). "This regulation is crucial in cancer, where IGF2BP2 can influence various aspects such as cell proliferation, apoptosis, and the cellular response to therapy." (PMID 39596216, 2024). "(E) Downregulated hallmarks of cancer upon IGF2BP2 KD in UMUC3 (p-value <0.05 for all shown pathways)." (PMID 39041323, 2024). "In cancer, lncRNAs have been shown to interact with m6A methylation, binding to IGF2BP2 to stabilize themselves." (PMID 39596216, 2024). "Insulin-like growth factor 2 mRNA binding protein 2 (IGF2BP2) is an RNA-binding protein that plays several important biological roles in disease metabolism and cancer." (PMID 38328550, 2024). "IGF2BP2 plays a key role in dysregulating programmed cell death, particularly in ferroptosis and autophagy, within cancer cells." (PMID 39596216, 2024). "Much research has indicated that METTL3 increases targeted mRNA stability in an IGF2BP2-dependent manner in cancers." (PMID 39095708, 2024). "This competitive binding interferes with IGF2BP2’s recognition of m6A-modified RNAs, thereby inhibiting their expression and suppressing cancer progression." (PMID 39596216, 2024). "A previous study has showed that IGF2BP2 was involved in the stabilisation of m6A‐marked transcripts in cancer cells." (PMID 38952035, 2024). "Studies have shown that IGF2BP2 can promote the growth of NSCLC cells, and is associated with drug resistance in various human cancers." (PMID 39731162, 2024). "In the TME, IGF2BP2 fosters immunosuppressive conditions by supporting TAMs and other immunosuppressive cells, which help cancer cells escape immune detection." (PMID 39596216, 2024). "Regardless of the specific role autophagy plays in different cancers, IGF2BP2 consistently functions as an oncogene." (PMID 39596216, 2024). "Insulin-like growth factor 2 mRNA-binding protein 2 (IGF2BP2) has been confirmed to play oncogenic role in many cancers." (PMID 39014364, 2024). "The role of IGF2BP2 in cancer malignancy was further accentuated by colony‐formation assays, where a significant reduction in the ability to form colonies was observed." (PMID 38682020, 2024). "IGF2BP2, a new RNA-binding protein, is highly expressed in various cancers and has been found to support tumor growth and progression." (PMID 39668820, 2024). "IGF2BP2’s ability to bind different RNAs is crucial for its role in cancer progression, as this binding influences a wide range of oncogenic processes." (PMID 39596216, 2024). "As an N6-methyladenosine (m6A) reader, IGF2BP2 is involved in cancer progression by binding to different RNAs." (PMID 39014364, 2024). "As an m6A reader, IGF2BP2 stabilizes m6A-modified RNAs, influencing gene expression in ways that support cancer cell stemness, proliferation, migration, and evasion of programmed cell death." (PMID 39596216, 2024). "This review provides a comprehensive summary of the mechanisms by which IGF2BP2 contributes to therapy resistance, with the aim of improving the efficacy of chemotherapy in cancer treatment." (PMID 39596216, 2024). "IGF2BP2 plays a key role in determining the cargo of EVs released by cancer cells, thereby modulating their effects on macrophages and promoting cancer cell migration." (PMID 39596216, 2024). "Additional analysis of HNSC specimens with their paired adjacent normal counterparts further demonstrated IGF2BP2 upregulation in HNSC cancer." (PMID 38250159, 2024). "Beyond mRNAs regulated by IGF2BP2, non-coding RNAs (ncRNAs) also play a role in regulating glucose metabolism in cancer cells." (PMID 39596216, 2024).
cancer (continued). "When we look at IGF2BP2’s expression pattern, it is found to vary significantly among G1, G2, G3, and G4 grades in a few cancer types." (PMID 39457524, 2024). "IGF2BP2 plays a critical role in cancer development, progression, and drug resistance by modulating m6A RNA modifications." (PMID 39596216, 2024). "Research on how IGF2BP2 regulates circular RNAs (circRNAs) in cancer is still limited, with only a few studies indicating that IGF2BP2 functions by recognizing and binding to m6A-modified sites in circRNAs." (PMID 39596216, 2024). "The IGF2BP family consists of three members including IGF2BP1, IGF2BP2, and IGF2BP3, all of which are implicated in the drug resistance of human cancers." (PMID 39731162, 2024). "We found that IGF2BP2 expression was fluctuated across different cancer types in comparison with their corresponding normal tissues." (PMID 38250159, 2024). "IGF2BP2 was also overexpressed in cancer cells from Patient 2 compared to other patients on both RNA and protein levels." (PMID 38012143, 2023). "Paired analysis of these 50 cancer and adjacent tissues revealed that IGF2BP2 is highly expressed in CRC." (PMID 37088822, 2023). "IGF2BP1 and IGF2BP3 are re-expressed in many types of tumors, and IGF2BP2 was also found to be excessively expressed in malignancies due to genomic amplification according to pan-cancer analysis with TCGA data." (PMID 37644505, 2023). "Some studies have proved that the m6A reader IGF2BP2 can be used as a post-transcriptional regulator to participate in the differentiation of cancer and cancer stem cells, such as hepatocellular carcinoma, liposarcoma, and glioblastoma." (PMID 36831377, 2023). "In the realm of human cancers, IGF2BP2, an m6A reader, demonstrates interactions with diverse RNA species, including miRNAs, mRNAs, and lncRNAs, thereby affecting cancer development and progression." (PMID 37841018, 2023). "Recent studies have shown increased expression of IGF2BP2 in cancer cells, and its expression levels have been shown to be associated with unfavorable prognosis." (PMID 37936610, 2023). "In LSCC cells, IGF2BP2 knockdown attenuated cancer cell aggressiveness by repressing cell proliferation, inhibiting cell invasion, and eliciting G0/1-phase arrest of cell cycle." (PMID 37816718, 2023). "On the other hand, five pleiotropic loci were detected in the all-cancer meta-analysis (e.g., IGF2BP2 on 3q27, PRMT6 on 1p13, and TRIM4 on 7q22)." (PMID 37340002, 2023). "scDNA-seq also confirmed that the IGF2BP2::TESPA1 fusion was cancer cell-specific, as suggested by long-read scRNA-seq data." (PMID 38012143, 2023). "Considering that the cell cycle plays an important role in cancer development, and previous experiments found that IGF2BP2 regulated cell cycle checkpoint markers expression in LSCC cells." (PMID 37816718, 2023). "Regarding cellular functions, CDK6 knockdown also significantly inhibited cell viability, colony formation ability, and cell invasion and elicited G0/1-phase arrest of cell cycle, whereas IGF2BP2 overexpression aggravated cancer cell aggressiveness." (PMID 37816718, 2023). "Emerging evidence suggests that IGF2BP2 is an N6-methyladenosine (m6A) reader that is involved in cancer progression by interacting with lncRNAs." (PMID 38040698, 2023). "With regard to cancer, an m6A score based on the expression of IGF2BP2, IGF2BP3, KIAA1429, METTL3, EIF3H, and LRPPRC was reported as an indicator of pancreatic tumor microenvironment status and was a potential biomarker for patients’ prognosis." (PMID 37903783, 2023). "In LSCC cells, IGF2BP2 knockdown attenuated cancer cell aggressiveness, possibly through modulating cell cycle arrest." (PMID 37816718, 2023).
cancer (continued). "Coherent with the high IGF2BP2 protein levels, IGF2 RNA, which is bound by the wt IGF2BP2 protein, is also largely overexpressed in Patient 2 cancer cells compared to other patients." (PMID 38012143, 2023). "Herein, we identified IGF2BP2 as a regulator of the m6A modification of CSF2, which in turn mediated the transformation of carcinoma-associated MSCs, which provides novel insights into the biological roles of m6A modification in MSC reprogramming in cancer." (PMID 37865637, 2023). "Considering that IGF2BP2 is involved in m6A modification and this RNA modification influences various cellular activities in cancers, further investigations are needed to understand the off-target effects and toxicity of JX5." (PMID 35915142, 2022). "This evidence indicates that IGF2BP2 promotes the proliferation, migration and invasion of cancer cells." (PMID 35299748, 2022). "We first evaluated the clinical significance of IGF2BP2 in human cancers and analyzed RNA-seq data from TCGA projects." (PMID 36257938, 2022). "N6‐methyladenosine (m6A) reader insulin-like growth factor 2 mRNA-binding protein 2 (IGF2BP2) participates in the initiation and growth of cancers by communicating with various targets." (PMID 35915142, 2022). "Although the roles of Slug in promoting EMT have been well studied, we further investigated the roles of Slug in IGF2BP2-regulated EMT of cancer cells." (PMID 34980207, 2022). "As an RNA-binding protein, insulin-like growth factor 2 mRNA-binding protein 2 (IGF2BP2) is involved in enhancing the progression of a few malignant tumors by recognizing N6-methyladenosine on targeted RNA." (PMID 36358799, 2022). "In a large number of pan-cancer samples (n=9500), the higher IGF2BP2 was significantly correlated with poorer survival of cancer patients (HR = 1.7)." (PMID 36281789, 2022). "Collectively, this study is the first to report on the discovery of the oncogenic role of IGF2BP2 in promoting lymphatic metastasis of HNSCC, indicating the broadly clinical significance of IGF2BP2 in cancer metastasis." (PMID 34980207, 2022). "This denotes that the cancer-promoting function of IGF2BP2 in CRC is achieved at least partially through the regulation of TUG1’s profile." (PMID 35014946, 2022). "Meanwhile, IGF2BP2 overexpression induces genome instability and promotes cancer cell proliferation and migration in vitro." (PMID 34980207, 2022). "Recently, a growing number of studies has shown that upregulated IGF2BP2 in cancer cells play a critical role in cell migration, invasion, and metabolic alteration." (PMID 35717493, 2022). "Our findings provide insight into a novel circRNA, circEIF3H, with significant cancer-promoting function via serving as a scaffold for IGF2BP2/HuR." (PMID 35568705, 2022). "The GSEA results showed that IGF2BP2 promotes the malignant progression of OSCC by affecting cancer-related processes (EMT, glycolysis, cell cycle, etc.)and immune-related biological functions and pathways." (PMID 35299748, 2022). "The regulatory effect of IGF2BP2 on cancer cell proliferation, migration, and invasion is an important factor contributing to prognosis." (PMID 35299748, 2022). "IGF2BP2 has been reported by multiple previous studies to be related to the development and metastasis of some cancers." (PMID 36358799, 2022). "M6A readers (YTHDF2, IGF2BP2, etc.)can work synergistically with m6A writers and erasers during the oncogenesis of various cancers." (PMID 35804965, 2022). "Emerging evidence shows that IGF2BP2 participates in the development and progression of cancers by communicating with different RNAs such as microRNAs, messenger RNAs, and long non-coding RNAs." (PMID 36185403, 2022). "We also used TCGA pan-cancer data to verify that IGF2BP2 was expressed at high levels in a variety of cancers and was related to a poor prognosis in patients." (PMID 35299748, 2022).
cancer (continued). "Oncomine and TIMER showed that IGF2BP2 expression status varies in different cancers and most cancer types present higher IGF2BP2 expression." (PMID 36281789, 2022). "In the realm of cancer research, IGF2BP2 is well-known for its regulation of differentiation potential in mouse neocortical neural precursor cells as well as myoblast proliferation, myogenesis, muscle cell motility, and energy consumption 14-16." (PMID 35919812, 2022). "Gene set enrichment analysis (GSEA) showed that IGF2BP2 led to a poor prognosis in OSCC by affecting cancer-related (epithelial-mesenchymal transition, glycolysis, cell cycle, etc.)and immune-related biological functions and pathways." (PMID 35299748, 2022). "These genes, potentially regulated by IGF2BP2, were enriched in many important cancer-related pathways." (PMID 36257938, 2022). "Recent studies have shown that IGF2BP2 aggravates growth and metastasis of various types of cancer via stabilizing mRNA or translation of important modulators." (PMID 35773744, 2022). "The results of the pan-cancer analysis also showed that IGF2BP2 was upregulated in a variety of cancers and was negatively correlated with the OS rate." (PMID 35299748, 2022). "In some previous studies, IGF2BP2 was reported to encourage the progression of a few malignant tumors, such as breast tumors, non-small-cell lung tumors, and bowel cancer." (PMID 36358799, 2022). "Mechanistically, IGF2BP2 modulates proliferation, migration, invasion, metastasis and apoptosis of cancer cells by regulation transcription of miRNAs, lncRNAs and other m6A-related genes." (PMID 33568150, 2021). "This suggests that the role of IGF2BP2 in cancers development varies among tumors and ethnic groups." (PMID 33568150, 2021). "Herein, we summarize the specific roles of IGF2BP2 in multiple cancers and provide a comprehensive view of IGF2BP2." (PMID 33568150, 2021). "As a result, we investigated the expression modes of 24 m6A regulatory genes in 33 cancers and explored the differential expression of IGF2BP2 in HNSCC and its clinical significance." (PMID 33816266, 2021). "The primary role of IGF2BP2 is to modulate cell metabolism; however, emerging studies have shown that IGF2BP2 is involved in various types of cancers 78-80." (PMID 34239358, 2021). "In colorectal cancer, lncRNA LINRIS modulates the expression of MYC to influence the process of glycolysis, leading to the progression of cancer by stabilizing IGF2BP2." (PMID 34295922, 2021). "IGF2BP2 was also reported to regulate the expression of glycolysis genes and thus switch cancer metabolism to adapt to environmental changes." (PMID 34696797, 2021). "This review describes the role and specific expression patterns of IGF2BP2 in human metabolic diseases and cancers." (PMID 33568150, 2021). "IGF2BP2 has been reported to stabilize mRNA and thus contribute to the progression of cancers, and Myc was reported to be the key target of IGF2BP2." (PMID 34696797, 2021). "IGF2BP2 was also reported to be involved in the progression of numerous cancers, and it was recently suggested as a potential biomarker predicting prognosis." (PMID 34696797, 2021). "The protein expression levels of PD-L1, PD-1 and IGF2BP2 were increased in the hypopharyngeal cancer tissues." (PMID 34608837, 2021). "First, the correlation of IGF2BP2 expression and immune infiltration levels was evaluated in diverse cancer types." (PMID 33816266, 2021). "In this review, we summarize the current knowledge on IGF2BP2 with regard to diverse human metabolic diseases and its potential for cancer prognosis." (PMID 33568150, 2021). "Numerous studies have shown that dysregulation of IGF2BP2 (IGF2 mRNA binding protein 2) can lead to the development of a variety of cancers." (PMID 33550985, 2021). "The interrelationship among IGF2BP2, miRNAs, lncRNAs and their target genes with regard to cancers and metabolic diseases are reported but inconclusive." (PMID 33568150, 2021).
cancer (continued). "In contrast, YTHDC1 recognises circNSUN2 and export it to the cytoplasm, eventually participating in cancer progression by forming the cir-cNSun2/IGF2BP2/HMGA2 complex." (PMID 35004679, 2021). "IGF2BP2 was involved in the development of various cancers including colorectal carcinoma, liver cancer and cervical cancer through recognizing m6A modified RNAs and regulating RNA stability and translation." (PMID 34149801, 2021). "As an mRNA-binding protein, IGF2BP2 is widely known to function as an essential oncogene via targeting lncRNAs and miRNAs, thereby promoting cancer cell invasion, proliferation and migration." (PMID 34608837, 2021). "Compared with normal samples, IGF2BP2 was significantly upregulated in nine cancer types and downregulated in two cancer types." (PMID 34589481, 2021). "Given that HNRNPA1 and IGF2BP2 have been widely discovered to be able to regulate the progression of various cancers, including HCC, these two candidate RBPs were selected to engage in the following experiments." (PMID 35173610, 2021). "The insulin-like growth factor 2 mRNA-binding protein 2 (IGF2BP2) is involved in the progression of multiple types of cancer." (PMID 34608837, 2021). "It has been demonstrated that IGF2BP2 promotes cancer progression by regulating the m6A-dependent glycolytic process and promotes cancer metastasis in the form of an RNA-protein ternary complex." (PMID 34993195, 2021). "The expression of IGF2BP2 in paired cancer tissues was also highly statistically significant (p = 3.333e-16)." (PMID 32391379, 2020). "IGF2BP2 imbalance can lead to the occurrence of many diseases, including insulin resistance, obesity, and cancer." (PMID 32391379, 2020). "In our research, IGF2BP2 was predicted to be closely related to the EMT pathway of cancer progression." (PMID 33323543, 2020). "At the cellular level, IGF2BP2 enhances genome instability and stimulates cancer cell proliferation and migration." (PMID 33246429, 2020). "METTL3 and IGF2BP2 (insulinlike growth factor 2 MRNA-binding protein 2) were overexpressed in colorectal cancer and promote the cancer progression." (PMID 33575259, 2020). "Gene set enrichment analysis revealed that scavenging and degradation, synthesis and metabolism, cell growth, death and motility, and cancer pathways were differentially enriched in patients with high IGF2BP2 expression." (PMID 32391379, 2020). "METTL3 and IGF2BP2 are key genes in the m6A signal pathway and have recently been shown to play important roles in cancer development and progression." (PMID 33224879, 2020). "Many studies have shown that the IGF2 mRNA-binding protein 2 (IGF2BP2) plays oncogenic roles in cancers." (PMID 31852504, 2019). "Previous studies have demonstrated that IGF2BP2 participates in the initiation and progression of numerous cancers." (PMID 31852504, 2019). "At the cellular level, IGF2BP2 enhances genomic instability and stimulates cancer cell proliferation and migration." (PMID 29736175, 2018). "Autoantibodies against cancer-specific autoantigens like IGF2BP2 represent a unique group of the new generation of biomarkers." (PMID 29736175, 2018). "Due to the different effects of IGF2BPs on IGF-II in varying cell types, the shielding effect of IGF2BP-2 and -3 needs further validation in other cancer types." (PMID 30733684, 2018). "IGF2BP2 could bind to and stabilize specific mRNA in tumors in an m6 A-dependent manner, influencing the proliferation of cancer cell lines in vitro, as well as tumorigenicity in vivo." (PMID 40597017, 2025). "This study provides compelling evidence for IGF2BP2 as a target in PLK1-overexpressing cancers." (PMID 40347943, 2025). "Our findings suggest that IGF2BP2 may serve as critical molecular mediators of cancer cell–CAF crosstalk, although the precise mechanisms warrant further investigation." (PMID 40362183, 2025). "Knockdown of HMGA2 or IGF2BP2 in a mouse xenograft model suppressed cancer growth." (PMID 40448344, 2025).